MT-TP (mitochondrially encoded tRNA-Pro (CCN))
Synonyms: trnP; formerly MTTP
Gene: Mitochondrial transfer RNA gene on chromosome MT (15,956 to 16,023, reverse strand). Ensembl gene ENSG00000210196.
Gene-disease validity (ClinGen):
ClinGen rates the evidence that MT-TP causes each of these diseases.
mitochondrial disease (mitochondrial): Definitive.
Diseases named in the same sentence as MT-TP in open-access papers:
MT-TP is named in the same sentence as 53 diseases in open-access papers, as found by Europe PMC text mining. Sharing a sentence is not in itself a finding about the gene and the disease. The quoted sentences say what the papers report.
abetalipoproteinemia (22 papers, 2010 to 2025). "Genetic analysis revealed likely pathogenic compound heterozygous variants, c.59_61 + 14del and c.1946A > G (p.Asn649Ser), in the MTTP gene associated with abetalipoproteinemia." (PMID 40870862, 2025). "Rare variants in MTTP gene have been linked with susceptibility to MAFLD and rare and loss-of-function mutations in MTTP result in abetalipoproteinaemia." (PMID 38662298, 2024). "Rare, loss-of-function mutations in MTTP can result in the recessive disorder abetalipoproteinaemia, where MTP deficiency causes defective lipoprotein biosynthesis having multiple severe effects including liver steatosis and fibrosis." (PMID 37484212, 2023). "Although no CNVs were found for any genes on our candidate gene lists, a large deletion was found in the MTTP gene in a person with the phenotype of abetalipoproteinemia, and this is certainly the cause of his low HDL-C (22 mg/dl)." (PMID 35460704, 2022). "Abetalipoproteinemia (ABL) is a homozygous autosomal recessive disorder caused by mutations of the MTTP gene." (PMID 33584351, 2021). "On the other hand, Koo (2013) has reviewed that hepatic steatosis can be observed in patients with ApoB100 mutation (hypobetalipoproteinemia) and MTTP mutation (abetalipoproteinemia)." (PMID 30060615, 2018). "Cases of MTTP gene mutation is characterized by abetalipoproteinemia and remarkable hepatic steatosis or cirrhosis." (PMID 26458397, 2015). "We discovered a novel mutation in MTTP gene and we confirmed the diagnosis of abetalipoproteinemia in new Tunisian families." (PMID 23556456, 2013). "Mutations introduced in either of the helices resulted in abolition of lipid binding, which provides an explanation for abetalipoproteinemia found in humans carrying point mutations in the MTTP gene." (PMID 20423497, 2010). "Loss of function mutations in the MTTP gene results in abetalipoproteinemia." (PMID 35931202, 2022). "Our group studies evolution and structure function of MTP to identify different amino acids and structural motifs participating in the transfer of different lipids and to understand molecular bases for the missense mutations in the MTTP gene in abetalipoproteinemia patients." (PMID 35931202, 2022). "Its role as an essential chaperone for the biosynthesis of apolipoprotein B (apoB)-containing triglyceride-rich lipoproteins was established after the realization that abetalipoproteinemia patients carry mutations in the MTTP gene resulting in the loss of its lipid transfer activity." (PMID 22353470, 2012). "We conclude that the main feature of the MTTP p.I564T variant is impaired ApoB secretion and hepatic lipid accumulation as a result of decreased lipid transfer activity distinct from the classical abetalipoproteinaemia phenotype where MTP expression is abolished." (PMID 37484212, 2023). "Abetalipoproteinemia (ABL) is a rare recessive condition caused by biallelicloss-of-function mutations in the MTTP gene encoding the microsomaltriglyceride transfer protein large subunit." (PMID 34078172, 2021). "Abetalipoproteinemia and homozygous hypobetalipoproteinemia are classical Mendelian autosomal recessive and co-dominant conditions, respectively, which are phenotypically similar and are usually caused by bi-allelic mutations in MTTP and APOB genes, respectively." (PMID 29540175, 2018). "However, mutations in the apoB gene can cause familial hypobetalipoproteinemia and mutations in MTTP, which encodes MTP, cause abetalipoproteinemia." (PMID 37095219, 2023). "Abetalipoproteinemia (ABL) is a rare disease, characterized by absence or very low apoB-containing lipoproteins in plasma and remarkable hepatic steatosis or cirrhosis, which is attributable to decreased lipid secretion from the liver and caused by MTTP gene mutation." (PMID 26458397, 2015). "However, patients with abetalipoproteinemia also manifest hepatic steatosis because they also lack MTTP in hepatocytes." (PMID 23145105, 2012).
abetalipoproteinemia (continued). "Just recently, Hendriks’ group used this technique to knock out the APOB and MTTP genes in human fetal hepatocyte-derived organoids, deletions of which are responsible for two monogenic lipid disorders predisposing to NAFLD: familial hypolipoproteinemia and abetalipoproteinemia." (PMID 37175830, 2023). "In relation to the current findings, it is worth noting that human subjects with abetalipoproteinemia (ABL) (in whom the MTTP gene is defective) have been shown to exhibit defective CD1 function as a result of impaired lipid antigen loading." (PMID 23805328, 2013). "We identified a rare causal variant c.1691T>C p.I564T (rs745447480) in MTTP, encoding microsomal triglyceride transfer protein (MTP), associated with progressive NAFLD, unrelated to metabolic syndrome and without characteristic features of abetalipoproteinaemia." (PMID 37484212, 2023).
Hepatic steatosis (19 papers, 2012 to 2025). Steatosis is a term used to denote lipid accumulation within hepatocytes. "Hepatic steatosis has been reported in subjects with mutations in MTTP, and pharmacologic inhibition or genetic deletion of MTTP caused hepatic steatosis." (PMID 36834959, 2023). "MTTP, which is involved in lipid metabolism, is affected by alcohol exposure and was reported to be associated with alcoholic fatty liver in the Korean population." (PMID 35864541, 2022). "Of concern, pharmacologic MTTP inhibition is associated with significant toxicities, including hepatic steatosis and increased liver aminotransferase levels." (PMID 32907986, 2020). "Genetic defect in MTTP or APOB gene is associated with liver steatosis, obesity, and insulin resistance." (PMID 30037134, 2018). "MTTP I128T is associated with a reduction in hepatic steatosis, plasma lipids, and apoB." (PMID 40507973, 2025). "•A rare MTTP variant, p.I564T, leads to progressive fatty liver disease and cirrhosis." (PMID 37484212, 2023). "Liver steatosis and fibrosis are more common in patients with low active genotype fatty liver, suggesting that MTTP gene polymorphism may affect the course of fatty liver." (PMID 35983527, 2022). "However, the promise of MTTP-targeted therapeutics has been questioned, as hepatic MTTP inhibition or MTTP deficiency induces hepatic steatosis and transaminitis." (PMID 32907986, 2020). "Thus, while MTTP inhibition clearly lowers plasma lipids and increases hepatic lipids, it is unclear how this hepatic steatosis is associated with or dissociated from a metabolically deleterious phenotype." (PMID 32907986, 2020). "We assumed genetic effect of the MTTP polymorphisms may interact with the metabolic regulators, such as age, sex, body mass index (BMI), and insulin resistance, to regulate the lipid homeostasis and hepatic steatosis." (PMID 26458397, 2015). "The hepatic secretion of VLDL is restrained by the inhibition of microsomal triglyceride transfer protein (MTP; gene name, MTTP), leading to an increase in hepatic steatosis and a reduction in serum lipids and apoB." (PMID 40507973, 2025). "Specific knockout of the MTTP gene in hepatocytes leads to the accumulation of a large amount lipids in mouse hepatocytes, and eventually results in hepatic steatosis and fatty liver." (PMID 36005631, 2022). "In mice, the genetic deletion of liver MTTP induces hepatic fat accumulation; however, despite hepatic steatosis, these mice demonstrated normal hepatic insulin sensitivity." (PMID 32907986, 2020). "Moreover, inhibited SHP can prevent the development of hepatic steatosis by increasing hepatic very-low-density lipoprotein secretion and by increasing MTTP levels." (PMID 34357017, 2021). "Apob mutant mice are quite phenotypically similar to MTTP-deficient mice, developing hepatic steatosis without a disruption in glucose or insulin tolerance." (PMID 32907986, 2020). "Additionally, MTTP KO mice were also shown to be unable to produce VLDLs, manifesting lower plasma triglyceride levels and hepatic steatosis." (PMID 31491968, 2019). "Microsomal triglyceride transfer protein (MTTP) deficient mice have reduced plasma triglycerides levels but develop hepatic steatosis without insulin resistance and inflammation." (PMID 23738334, 2013). "Thus, MTTP deficiency does not alter hepatic or peripheral insulin action in young mice despite marked hepatic steatosis and increases in sn-1,2-DAGs in the lipid droplet fraction." (PMID 32907986, 2020). "In MTTP-knockout mice, there was a striking reduction in VLDL triglyceride accompanied by hepatic steatosis." (PMID 28953935, 2017). "Pathogenic variants were detected in the ABCB4 gene in a patient with idiopathic cholestasis, in the APOB and CP genes in a patient with hepatic steatosis, in the ABCB4 gene in a patient with elevated liver enzymes, and in the MTTP and AGL genes in a patient with cryptogenic cirrhosis." (PMID 40870862, 2025).
Hepatic steatosis (continued). "Prior investigations have observed that MTTP knockout mice develop hepatic steatosis, with increased DAG and ceramide content but without the development of hepatic insulin resistance or glucose intolerance." (PMID 32907986, 2020). "MTTP and APOCIII are responsible for the assembly, formation, and release of VLDL from the hepatocytes and are regulated by the FOXOa1 and can contribute to hepatic steatosis, so we checked their gene expression and we saw a decreased level of both in the hepatocytes of the compound-treated group." (PMID 39759127, 2024).
steatosis (9 papers, 2013 to 2025). Increased lipid within the cytoplasm of cells. "The conditional liver-specific HNF4α disruption in mice led to severe steatosis and reduced serum triglycerides, which were associated with the selective disruption of ApoB and MTTP genes’ expression." (PMID 36362837, 2022). "The present study also investigated the I128T SNP of the MTTP gene, and the risk of steatosis was 8.51-fold higher in patients with the IT/TT genotype of the I128T SNP when combined with HCV genotype 3 infections." (PMID 36027755, 2022). "Finally, we leveraged the APOB- and MTTP-mutant organoids to establish a CRISPR-based screening platform to identify steatosis modulators/targets and to evaluate NAFLD risk genes." (PMID 36823355, 2023). "Human fetal hepatocyte organoids model NAFLD steatosis under three triggers: fatty acid overload, PNPLA3 I148M mutation, and APOB/MTTP mutations." (PMID 40475995, 2025). "APOB−/− and MTTP−/− mutant organoids constitute a natural steatosis organ model and can be maintained in long-term culture at levels that maintain a stable level of steatosis." (PMID 37175830, 2023). "Both APOB−/− and MTTP−/− mutants constitute natural steatosis organoid models that can, like their WT counterparts, be long-term expanded in culture for at least 2 years with stable steatosis levels." (PMID 36823355, 2023). "Steatosis is caused by three main triggers: overload nutritional diet, high risky variant (PNPLA3 I148M) and predisposed monogenic lipid disorders (APOB or MTTP mutation)." (PMID 37009924, 2023). "Liver-specific conditional knockout of HNF4α in adult mice led to severe steatosis associated with disruption of VLDL secretion and misregulation of ApoB and MTTP expression." (PMID 31781248, 2019). "There was a positive correlation between the histological grade of steatosis and reduction in the MTTP mRNA." (PMID 23554788, 2013). "We selected 17 candidate NAFLD drugs from recent drug development programs and from new targets reported in the literature, focusing on those with putative hepatic effects, and screened these drugs in the FFA-induced and genetic (APOB−/− and MTTP−/−) steatosis models." (PMID 36823355, 2023). "Previously established APOB−/−or MTTP−/−organoids exhibited severe steatosis phenotype, and could be passaged for long-term expansion." (PMID 37009924, 2023). "Here we use human fetal hepatocyte organoids to model the first stage of NAFLD, steatosis, representing three different triggers: free fatty acid loading, interindividual genetic variability (PNPLA3 I148M) and monogenic lipid disorders (APOB and MTTP mutations)." (PMID 36823355, 2023). "For the FFA model, WT organoids were first made steatotic with a fixed concentration of FFAs (500 μM) for 3 days before drug administration, to induce a degree of steatosis similar to that observed in APOB−/− and MTTP−/− organoids." (PMID 36823355, 2023). "In HCV-3 induced steatosis, the MTP activity and the MTTP mRNA level were both reduced." (PMID 23554788, 2013). "Using steatosis score as the readout, they scanned a panel of anti-NAFLD drugs (positive on animal models), and found inhibitors of ACC, FAS and DGAT2, a FXR agonist, as well as recombinant hFGF19 could efficiently alleviate the steatosis in FFA models and APOB−/−or MTTP−/− models." (PMID 37009924, 2023).
metabolic syndrome (5 papers, 2013 to 2023). A cluster of metabolic risk factors for CARDIOVASCULAR DISEASES and TYPE 2 DIABETES MELLITUS. "Previous reports have demonstrated subjects with MTTP promoter -493G/T or I128T polymorphisms are susceptible to develop metabolic syndrome, hyperlipidemia, more oxidative stress, ischemic heart disease, β-cell dysfunction and non-alcoholic steatohepatitis." (PMID 26458397, 2015). "Several MTTP polymorphisms have been reported relating to metabolic syndrome, hyperlipidemia and steatohepatitis." (PMID 26458397, 2015). "MTTP, which has associations with metabolic syndrome, body mass index, and insulin regulation, showed a strong signature of selection in Southeast Asians, including Indonesians." (PMID 23349834, 2013).
familial hypercholesterolemia (4 papers, 2020 to 2026). An inheritable form of hyperlipidemia, in which there are excess lipids in the blood. "Recently, the MTTP inhibitor lomita-pide has been registered on the European and US markets for the treatment of unresponsive homozygous familial hypercholesterolemia, despite some limitations regarding its side effects." (PMID 32882484, 2020).
Insulin resistance (4 papers, 2018 to 2025). Increased resistance towards insulin, that is, diminished effectiveness of insulin in reducing blood glucose levels. "Dysregulation of MTTP expression can lead to many diseases, such as lipid metabolism disorders, insulin resistance and cardiovascular diseases." (PMID 40213543, 2025). "Studies have shown that in animal models of diabetes or insulin resistance, the MTTP mRNA expression and activity in the intestine are increased, and the content of triglycerides in chylomicrons are increased." (PMID 34443619, 2021). "To better understand the effects of MTTP ablation over time, we studied both young and aged liver-specific MTTP knockout mice (L-Mttp−/−), assessing the development of lipid-induced hepatic insulin resistance." (PMID 32907986, 2020).
hepatoma (3 papers, 2017 to 2025). "The endogenous MTTP gene was ablated in human hepatoma Huh-7 cells using single guide RNA and RNA-guided clustered regularly interspaced short palindromic repeats-associated sequence 9 ribonucleoprotein complexes." (PMID 35931202, 2022). "We hypothesized that ablation of the MTTP gene in human hepatoma cells might avoid the need to transfect large plasmids expressing human apoB100." (PMID 35931202, 2022). "Therefore, we hypothesized that knockout of the endogenous MTTP gene in hepatoma cells may avoid the need to transfect cells with large apoB100 expressing plasmids for secretion studies." (PMID 35931202, 2022).
non-alcoholic fatty liver disease (3 papers, 2022 to 2023). "More recently, human fetal hepatocyte organoids were used for modeling free fatty acid loading, interindividual genetic variability (PNPLA3 I148M), monogenic lipid disorders (APOB and MTTP mutations), and induced non-alcoholic fatty liver disease (NAFLD)." (PMID 37146581, 2023). "Mutations in the MTTP gene have also been shown to play a role in the development of nonalcoholic fatty liver disease." (PMID 36026493, 2022). "A rare genetic variant in the gene MTTP has been identified as responsible for the development of severe non-alcoholic fatty liver disease in a four-generation family with no typical disease risk factors." (PMID 37484212, 2023).
Cirrhosis (2 papers, 2015 to 2023). A chronic disorder of the liver in which liver tissue becomes scarred and is partially replaced by regenerative nodules and fibrotic tissue resulting in loss of liver function. "Here we have clinically characterised a large four-generation family found to have a rare MTTP variant located at the interface with PDI resulting in progressive NAFLD, with consequent cirrhosis, liver failure, and HCC in homozygotes." (PMID 37484212, 2023).
Glucose intolerance (2 papers, 2020 to 2024). Glucose intolerance (GI) can be defined as dysglycemia that comprises both prediabetes and diabetes. "Furthermore, the results of HOMA-IR, ITT, and GTT assays demonstrated that the beneficial effect of hepatocyte ChREBP deficiency on IR and glucose intolerance was blocked by hepatic MTTP overexpression." (PMID 38532128, 2024).
hyperlipidemia (2 papers, 2015 to 2018). "The increase in intestinal MTTP expression can be observed in high-cholesterol and HF diet-fed inositol-requiring enzyme 1 (IRE1β)-deficient mice, leading to hyperlipidemia and fatty liver." (PMID 30060615, 2018).
hypertriglyceridemia (2 papers, 2018 to 2021). A laboratory test result indicating elevated triglyceride concentration in the blood. "ChREBP enhances VLDL secretion in part through regulation of MTTP, and variants in the ChREBP locus are associated with hypertriglyceridemia in humans." (PMID 34684643, 2021).
type II diabetes (2 papers, 2022 to 2023). "Finally, the nonsynonymous SNP rs3816873 in the MTTP gene (iHS = 2.43, P = 0.015) was found to significantly associate with lower levels of insulin, blood pressure, and prevalence of type II diabetes in a European population." (PMID 36026493, 2022).
alcoholic fatty liver disease (1 paper, 2022). Lipid infiltration of the hepatic parenchymal cells that is due to alcohol abuse. "As the near downstream gene of C4orf17, MTTP has been suggested to be related to alcoholic fatty liver disease, possibly because alcohol exposure could increase triglyceride and cholesterol levels." (PMID 35864541, 2022).
co-infection (1 paper, 2014). "maxima co-infection compared with uninfected controls (ANXA1, HSP90B1, VEGFA, MTTP, TNFSF11B, TCF12, APP, and CXCL14)." (PMID 25504150, 2014).
hypothyroidism (1 paper, 2025). Abnormally low levels of thyroid hormone. "The effects of hypothyroidism (treatment factor) were significant for the content of MTTP, CD36, PEPT1, and GLUT2 proteins, while the interaction between time and treatment was significant only for L-FABP content." (PMID 39958687, 2025). "The hypothyroidism disrupts L-FABP, CD36, PEPT1, and GLUT2 circadian rhythms, reduces the MTTP amplitude, and punctually decreases the FATP4 content at the moment of the light to dark photoperiod transition." (PMID 39958687, 2025). "In addition, the hypothyroidism reduced L-FABP content at ZTs 16 and 20, FATP4 at ZT12, MTTP at ZT20, PEPT1 at ZT 8 (while P = 0.09 was depicted at ZT4), and GLUT2 at ZT16 according to the pairwise comparisons." (PMID 39958687, 2025).